ATF4 (activating transcription factor 4)
Diseases named in the same sentence as ATF4 in open-access papers (continued):
Sharing a sentence is not in itself a finding about the gene and the disease.
breast cancer (continued). "In contrast, the expression of these genes was highly correlated with Sirt5 in brain cancer (Pearson values: sin1 0.96; PRCA 0.92; Nrf2 0.96; ATF4 0.97) and demonstrated the characteristic bimodal distribution observed in breast cancer." (PMID 35963851, 2022). "To follow up on the similarity between pathway gene expression patterns in breast cancer and brain cancer, we examined how the expression of ATF4 and/or Sirt5 was affected in the glioblastoma cell line LN229 upon glutamine withdrawal." (PMID 35963851, 2022). "To investigate C/EBPδ expression in response to ER stress, we first used thapsigargin, which induced C/EBPδ protein levels along with the UPR effectors XBP1S and ATF4 in multiple cancer cell lines representing melanoma and breast cancer." (PMID 34725321, 2021). "In particular, ATF4 expression is elevated in some tumours, such as breast cancer and colorectal cancer, compared to matched normal tissues, especially in hypoxic and nutrient deficient regions of tumour tissues." (PMID 34709767, 2021). "As SLC38A2 was upregulated during different stresses and degraded by autophagy, we investigated if the expression of SLC38A2 correlated with ATF4 and autophagic markers in breast cancer patients." (PMID 33028955, 2021). "In breast cancer, the PERK branch of the UPR increases cell migration upon hypoxic induction through ATF4-mediated induction of lysosomal-associated membrane protein 3 (LAMP3), a lysosomal protein that is also relevant to cancer metastasis." (PMID 33746610, 2021). "This critical roles of ATF4 in cancer can explain the pro-metastatic function of PERK in breast cancers, as PERK depletion effectively mitigates the metastatic lesions developed in a Her2-driven breast cancer model." (PMID 34746012, 2021). "ATF4 plays vital roles in several human cancer types, such as breast cancer, colon cancer, and prostate cancer." (PMID 34976799, 2021). "Previous studies also demonstrated that the inhibition of ATF4 expression reduces cell migration, invasion, and proliferation in breast cancer." (PMID 34976799, 2021). "In this study, we observed a negative correlation between members of the AKT/mTOR pathway and CHOP and ATF4 in breast cancer, both of which are downstream of PERK." (PMID 32508655, 2020). "PSAT1 can be directly activated by ATF4 and its expression is significantly increased in a variety of tumors, including breast cancer, ESCC, etc.." (PMID 32974142, 2020). "First, we used the GEPIA dataset to study the AKT/mTOR pathway members in breast cancer in relation to CHOP or ATF4, both of which are downstream of PERK." (PMID 32508655, 2020). "We observed a negative correlation between the AKT/mTOR pathway members and CHOP and ATF4 in breast cancer." (PMID 32508655, 2020). "Together, these clinical data indicate that ATF4 plays an important role in HER2-positive breast cancer patients." (PMID 31064130, 2019). "HER2 activation is critical in breast cancer development and ATF4 has been shown to play a role in breast cancer migration." (PMID 31064130, 2019). "Recently, it has been shown that ATF4 stimulates expression of LAMP3 in facilitating breast cancer cell migration and directly transactivates HO-1 (heme oxygenase 1) gene expression to inhibit anoikis and to promote tumor metastasis." (PMID 31064130, 2019). "Evidence indicates low ATF4 expression in multiple cancers, such as human breast cancer and ovarian carcinoma." (PMID 31534554, 2019). "Treatment of breast cancer cells with doxorubicin effectively increases the phosphorylation of eIF2α but suppresses the expression of ATF4 at the transcription level." (PMID 30155480, 2018). "Downstream of PERK, ATF4 mediates hypoxia-induced breast cancer progression via regulation of tribbles homolog 3 (TRIB3), unc-51-like autophagy activating kinase 1 (ULK1), and lysosomal-associated membrane protein 3 (LAMP3)." (PMID 30248920, 2018).
breast cancer (continued). "Elevated ATF4 expression has been observed in breast cancer cells, both in vivo and in vitro, and high CHOP expression in a cohort of 250 breast cancer patients was associated with increased disease-free survival." (PMID 30248920, 2018). "We treated MCF-7 human breast cancer cells with increasing concentrations of adenovirus vector expressing IL-24 (Ad.IL-24) for 72 h, and analyzed the expression of ATF4 protein by Western blot." (PMID 30424508, 2018). "Our studies show for the first time that cyclic adenosine monophosphate (cAMP)-dependent protein kinase A (PKA) activation is required for IL-24-induced cell death in a variety of breast cancer cell lines and this event increases ATF4 activity." (PMID 30424508, 2018). "In these two models, ATF4 overexpression facilitates the macrophage infiltration into breast cancer tissues via enhanced secretion of M-CSF and thus promotes tumor angiogenesis and tumor growth indirectly via recruiting proangiogenic macrophages." (PMID 25883982, 2015). "In this study, we found that exogenous overexpression of ATF4 in mouse breast cancer cells promotes tumor growth via increasing tumor microvascular density." (PMID 25883982, 2015). "Some members of this gene family are protective against breast cancer but others such as ATF4, ATF5, and CREB, promote breast cancer pathology." (PMID 24586334, 2014). "Likewise, lapatinib has been found to sensitize breast cancer cells to ferroptosis via ATF4-dependent transcriptional responses." (PMID 40688501, 2025). "Consistently, CRELD2 has been shown to be transcriptionally regulated by ATF4 in breast cancer." (PMID 40821803, 2025). "This bidirectional regulatory relationship forms the foundation of the ATF4-Gln axis—a key mechanism by which cancer cells adapt to microenvironmental stress (Hypoxia-mediated ATF4 induction promotes survival in detached conditions in metastatic murine mammary cancer cells)." (PMID 40830338, 2025). "ATF4 also mediated resistance of breast cancer cells treated with bortezomib by upregulating LC3B." (PMID 38601083, 2024). "ATF4 has been found to play a key role in occurrence and progression of breast cancer." (PMID 38601083, 2024). "This highlights the crucial role of ATF4 in Keto diet–induced metastasis of breast cancer cells." (PMID 38838145, 2024). "This suggests that while inhibiting PERK may promote apoptosis, the involvement of ATF4 and autophagy regulation adds complexity, requiring a comprehensive understanding of the overall cellular response in breast cancer." (PMID 38468244, 2024). "They found that Creld2 is regulated by PERK-modulated ATF4 via a putative C/ebp-Atf response element (CARE) in the promoter sequences of Creld2, and CRELD2 depletion suppresses tumor progression, indicating that the paracrine ROCK-PERK-ATF4-CRELD2 axis promotes breast cancer progression." (PMID 36936176, 2023). "ATF4 is highly expressed in triple-negative breast cancer, and ATF4 could promote breast cancer cell proliferation." (PMID 36900220, 2023). "However, we have found a distinct correlation of ER stress mediated ATF-4 upregulation with AMPK activation which is an essential prerequisite for autophagy induction leading to an ultimate senescence cascade in breast cancer cells." (PMID 36465376, 2022). "In addition to its canonical roles, ATF4 can promote migration and invasion in different types of cancers, including breast cancer, esophageal cancers, and bladder cancers." (PMID 34746012, 2021). "Activation of this UPR branch may induce EMT under hypoxic stress where the PERK/ATF4/LAMP3 arm of the UPR increases breast cancer cell migration and invasion induced under moderately hypoxic condition (1% O2)." (PMID 33746610, 2021). "Similarly, PERK also contributes to ECM reorganization in breast cancer and overexpression of ATF4, which is a component of PERK pathway, induces cell invasion and metastasis, stimulating MMP2 and MMP7 expression in ESCC." (PMID 33014334, 2020).
breast cancer (continued). "Moreover, reduction of the SBP enzymes was also observed in breast cancer cell lines upon the silencing of ATF4, in agreement with previous data." (PMID 32783398, 2020). "ATF4 expression was significantly upregulated in HER2-positive breast cancers." (PMID 31064130, 2019). "Expression of ATF4 also downregulated E-cadherin expression in breast cancer MCF7 cells." (PMID 31064130, 2019). "In this study, we showed that upregulated ATF4 expression is correlated with HER2-positive breast cancer specimens, suggesting that the ATF4 may play a role in HER2-mediated breast cancer development." (PMID 31064130, 2019). "Radiation treatment of breast cancer cells induces the PERK/ATF4/LAMP3 pathway." (PMID 30248920, 2018). "We performed Western blotting for ATF4 protein in breast cancer cells treated with BenSer for 6 h to determine whether BenSer-induced disruption of amino acid homeostasis was sufficient to induce the AAR pathway." (PMID 29940911, 2018). "Studies also found that arsenic-induced apoptosis of the breast cancer cells occurred mainly by activating the ER stress associated proteins including C/EBP homologous protein (CHOP) and activating transcription factor 4 (ATF4)." (PMID 28936164, 2017). "Moreover, hypoxia occurring in breast cancer stimulates the migration of cancer cells upon activation of the PERK/eIF2α-P/ATF4 signaling pathway." (PMID 27802179, 2016). "Overall, we concluded that exogenous overexpression of ATF4 in breast cancer cells may facilitate the recruitment of macrophages into tumor tissues and promote tumor angiogenesis and tumor growth indirectly." (PMID 25883982, 2015). "In this study, we demonstrated that exogenous overexpression of ATF4 in mouse breast cancer cells can increase proangiogenic macrophages infiltrating into tumor tissues via the secretion of M-CSF, thus promoting the tumor angiogenesis and also tumor growth indirectly." (PMID 25883982, 2015). "In this study, we overexpressed ATF4 in mouse breast cancer 4T1 and 4TO7 cells." (PMID 25883982, 2015). "The PERK/ATF4/LAMP3 arm of the UPR might function as a new target for therapy combating hypoxia-induced metastasis in breast cancer." (PMID 23294542, 2013). "Thus, the PERK/ATF4/LAMP3-arm of the UPR is an additional pathway mediating hypoxia-induced breast cancer cell migration." (PMID 23294542, 2013). "However, in the human breast cancer cell line MDA-MB 435 ATF4 mRNA levels were unaffected by pO2 whereas protein levels were highly elevated during near-anoxic conditions, strongly suggesting that regulation is mainly at the level of translational efficiency." (PMID 21306648, 2011). "Finally, we conducted knockout experiments targeting the HIF-1α, ATF4 and the programmed cell death 6 interacting protein (PDCD6IP) gene, which encodes the Alix protein, to investigate their roles in tramadol-induced cell death in breast cancer cells." (PMID 41526224, 2026). "In addition, upregulated expression of ATF4 was found in HER2-positive breast cancer specimens." (PMID 31064130, 2019). "FAD mediates PPARγ activity and induces apoptotic cell death through the PERK -eIF2α-ATF4-CHOP axis, the upregulation in Nox4 expression, and the production of cytosolic Ca2+ and ROS in breast cancer cells." (PMID 39765861, 2024). "Together, our results underscore the pivotal role of ATF4, in collaboration with BACH1, in shaping the transcription of pro-metastatic genes and metastatic capacity of breast cancer cells under Keto diet condition." (PMID 38838145, 2024). "-ROCK activation in mammary cancers yielded a tumour-promoting fibroblast phenotype through paracrine CRELD2;- ROCK activation in mammary cancers induced ATF4-regulated Creld2 transcription." (PMID 36936176, 2023). "In breast cancer, radiotherapy triggers the PERK-pathway of the UPR, and this is induced by increased PERK protein levels, phosphorylated eIF2α, ATF4, and LAMP3." (PMID 36675080, 2023).
breast cancer (continued). "Aghaei reported that a sesquiterpene from Pimpinella haussknechtii caused apoptotic death through activation of PERK branch by mark increase of ATF4, followed by an increase in CHoP and GADD34 in MCF-7 breast cancer cells." (PMID 34567171, 2021). "Similar data were obtained in KPL-4 and four additional breast cancer cell lines (MDA-MB-468, BT-549, MCF-7, MDA-MB-231) albeit with varying kinetics and relationships to XBP1S, ATF4, and/or CHOP expression." (PMID 34725321, 2021). "In melanoma and breast cancer cell lines, PERK mediated early induction of C/EBPδ through ATF4-independent pathways that involved at least in part Janus kinases and the STAT3 transcription factor." (PMID 34725321, 2021). "Confirming the role of IKKε/ATF4 observed in our HEK model cell line, silencing of IKKε in a panel of breast cancer cell lines had the opposite effect." (PMID 32783398, 2020). "We found that the promoter regions of PSAT1 and PHGDH contain binding sites for MYC-controlled activating transcription factor 4 (ATF4), which was reported to regulate PSAT1 expression in breast cancer." (PMID 32138178, 2020). "Previous work from our lab showed that upregulation of DR5 at the mRNA level following ONC201 treatment in colorectal cells was blocked by knockdown of ISR mediators ATF4 and CHOP and that ONC201 treatment activates an ISR in breast cancer cells." (PMID 33144917, 2020). "In the human breast cancer cell line MCF-7, TMEM33 interacted and stimulated both the PERK/p-eIF2α/ATF4/CHOP and IRE1α-XBP1-S signaling pathways." (PMID 31048699, 2019). "Increased expression of ATF4 was found as advantageous for MCF7 and SUM52PE breast cancer cell survival while recovering from acidosis and hypoxia treatment." (PMID 25988385, 2015). "In breast cancer, the PERK/ATF4/LAMP3-arm of the UPR is an additional pathway mediating hypoxia-induced tumor cell migration." (PMID 25078779, 2014). "A recent report demonstrated that BZ treatment induced autophagy in the breast cancer cell line MCF-7 by the proteasomal stabilization of ATF4 and ATF4-dependent upregulation of LC3B." (PMID 23546223, 2013). "BZ has been reported to induce autophagy via proteasomal stabilization of activating transcription factor 4 (ATF4) and up-regulation of LC3B by ATF4, thus preventing BZ-induced cell death in MCF7 breast cancer cells." (PMID 22200786, 2012). "In breast cancer cells, UPR-dependent upregulation of the activating transcription factor 4 (ATF4) has been shown to induce cytoprotective autophagy in hypoxic cells." (PMID 22190938, 2011). "Inhibition of phosphoserine aminotransferase 1 (PSAT1), a downstream target of ATF4, was proposed in estrogen receptor–negative breast cancer." (PMID 39964754, 2025). "The results revealed that breast cancer tissues exhibited lower expression levels of SAT1, ALOX5, ALOX12, ATF3, ATF4, GPX4 and NFE2L2 compared to normal tissues; conversely, higher expression levels of ALOX15, ALOXE3 and HO‐1 were observed in breast cancer tissues than in normal tissues." (PMID 38516826, 2024). "Similar to HCC cells, we have also found that YAP/TAZ and ATF4 repress ferroptosis by inducing SLC7A11 expression in other cancer cell types, including HT1080 fibrosarcoma and MDA‐MB‐231 breast cancer cells, suggesting a potentially high generality of the results." (PMID 34664408, 2021). "Rao and colleagues found that HDAC6, the regulator of endoplasmic reticulum stress in breast cancer cells, inhibits endoplasmic reticulum stress through deacetylation of glucose-related protein 78 (GRP 78) and suppression of activating transcription factor 4 (ATF4)-mediated osteogenesis." (PMID 32375326, 2020). "A detailed analysis in our SUM159 breast cancer cell system of key proteins involved in the 3 different UPR branches showed decreased expression of the chaperone Grp78 and the transcriptions factors ATF4, ATF6, sXBP1, and CHOP." (PMID 29295867, 2018).
breast cancer (continued). "In an invasive breast cancer cell line, GRB2 was found to regulate GTPases activation, and may also trigger ATF4 and ATF6." (PMID 28767067, 2017). "We found that CHAC1 is one of the largest changes in the gene expression induced by cystine starvation in the three TNBC cells, and that there is a significant positive correlation between ATF4 and CHAC1 gene expression in breast cancer patients and breast cancer cell lines." (PMID 29383104, 2017). "In addition, immunocytochemistry reveled that CDDO-Me markedly upregulated ATF4 and CHOP in nuclei, indicating that CDDO-Me is an effective ER stress inducer in breast cancer cells." (PMID 26053096, 2015). "In addition, hypoxia was found to stimulate the migration of breast cancer cells via the PERK/ATF4/LAMP3-arm of the unfolded protein response, suggesting a role of ATF4 in cancer metastasis." (PMID 25078779, 2014). "First, we observed a difference in ATF4 localization between feline and canine mammary cancer cells, irrespective of BB-CLA treatment, and so we like to postulate that these inherent differences may be reflective of the tumoral malignancy in vivo." (PMID 29649984, 2018). "In breast cancer (BC), the PERK/ATF4 pathway could be inhibited to mitigate radioresistance, sensitizing tumours to radiotherapy." (PMID 39072992, 2024). "γ-tocotrienol induced mammary tumor cell apoptosis and autophagy with JNK & p38 (but not ERK) activation and early upregulation of Grp78, TRB3, CHOP and ERS markers (IRE1α, phosphor-PERK, phosphor-eIF2α ATF4)." (PMID 37111076, 2023). "Given the fact that the ER stress inducer PERK was more expressed in breast cancer cells lacking STARD7, we also look at levels of other ER stress downstream targets such as Eukaryotic Initiation Factor 2α (EIF2α), X box‐binding protein 1 (XBP1) and Activating transcription factor 4 (ATF4)." (PMID 40443279, 2025).